MT4 (metallothionein 4)
Diseases named in the same sentence as MT4 in open-access papers (continued):
Sharing a sentence is not in itself a finding about the gene and the disease.
cancer (12 papers, 2012 to 2025). A tumor composed of atypical neoplastic, often pleomorphic cells that invade other tissues. "During the inflammatory process, cytokine production by immune cells is associated with cancer in multiple ways, although information on the contribution of MT4-MMP to the tumor immune response is very limited." (PMID 37373092, 2023). "In this context, MT4-MMP has been linked to cancer dissemination." (PMID 37373092, 2023). "Interestingly, its role in cancer progression may be linked to MT4-MMP’s contribution to the stability and permeability of the tumor vasculature." (PMID 37373092, 2023). "MMP-17 (MT4-MMP) is associated with inflammation and angiogenesis and is related to the progression of various cancers." (PMID 39796177, 2025). "NTN1 inhibition also reduced VIM expression and increased E-cadherin expression in GFP-labeled mT4 cancer cells." (PMID 40777309, 2025). "MT4-MMP-dependent cancer cell migration and invasion in vitro has been attributed to its dimerization through cysteine residues." (PMID 37373092, 2023). "The implication of MT4-MMP in cancer progression is related to its capacity to regulate intrinsic tumor cell proliferation and tumor blood vessel destabilization phenomenon." (PMID 37373092, 2023). "The expression of MT4-MMP and HIF-1α in these tumors was associated with poor overall survival of cancer patients." (PMID 37373092, 2023). "Cancer cells isolated from human samples and grown in 3D cell cultures in vitro or in mouse xenografts showed an upregulation of MT4-MMP during the acquisition of an invasive phenotype." (PMID 37373092, 2023). "Another consideration is to check for MT4-MMP partners that enhance cancer cell and stroma cell migration and malignancy." (PMID 37373092, 2023). "In this study, MT4-MMP was demonstrated to promote cancer cell proliferation only in 3D cell cultures and through the activation of the epidermal growth factor receptor (EGFR) after its binding to ligands." (PMID 37373092, 2023). "Similar to many other MMPs, clear roles for MMP-17 (also called MT4-MMP) have been described within the context of cancer." (PMID 34255809, 2021). "The role of MT4-MMP in the regulation of vessel stability in cancer and vascular diseases is well established." (PMID 30654475, 2019). "Given its contribution to different pathologies, particularly cancers, MT4-MMP represents an interesting therapeutic target." (PMID 30654475, 2019). "Most importantly, MT-4 also decreased heat shock protein 27 expression and reduced its interaction with caspase-3, which inured cancer cells to chemotherapy resistance." (PMID 25874627, 2015). "Taken together, these data emphasize the relevance of MT4-MMP in the context of cancer." (PMID 37373092, 2023). "Most of our current information regarding MT4-MMP comes from cancer studies." (PMID 37373092, 2023). "In addition, MT4-MMP-mediated cancer dissemination has been described in other types of tumors including colon and head and neck squamous cell cancer (HNSCC)." (PMID 37373092, 2023). "Finally, MT4-MMP is a relevant biomarker of malignancy that can be used for monitoring cancer progression in patients as well as a potential target for future therapeutic drug development." (PMID 37373092, 2023). "Interestingly, MT4-MMP is not only restricted to cancer cells, since positive staining was also observed in nearby cancer stromal cells, supporting its importance in the process of tumor invasion and metastasis." (PMID 37373092, 2023). "In contrast to the well-known MT1-MMP-mediated outside-in cell signaling, the signaling role of GPI-anchored MT4-MMPs in promoting cancer cell proliferation is unknown." (PMID 37373092, 2023). "On the other hand, only 60 scientific articles are proposed for MT4-MMP in cancer." (PMID 30654475, 2019). "Consistent with our mT4 findings, NTN1 overexpression in Panc02 cells shortened mouse survival and increased the histological tumor burden and Ki-67+ proliferating cancer cells in a splenic injection model." (PMID 40777309, 2025).
cancer (continued). "This will help us to develop new therapeutic approaches and to improve the design of new selective MT4-MMP inhibitors to achieve faster diagnosis and more personalized treatment for cancer patients and for vascular diseases." (PMID 37373092, 2023). "Both EGFR and MT4-MMP have been shown to cooperate in tumor cell invasion and signaling, driving cancer cell growth through the regulation of cell cycle proteins such as CDK4 activation and retinoblastoma protein inactivation." (PMID 37373092, 2023). "We further probed the changes in macrophage and monocyte phenotypes in both MT4 and NDL cancer models." (PMID 36451859, 2022). "However, further investigations are essential to improve our knowledge about the function of MT4-MMP in the embryo as well as in physiological and pathological conditions including cancer progression." (PMID 37373092, 2023). "In line with this, the HM-7 cancer cell line expresses MT4-MMP in lipid rafts, while caveolin-1 is not detected." (PMID 37373092, 2023). "MT4-MMP is thought to stimulate cell proliferation by interacting with EGFR and enhancing its activation by its ligands, the epidermal growth factor (EGF), and tumor growth factor (TGF) in cancer cells." (PMID 37373092, 2023). "Together, these data support the hypothesis that MT4-MMP induces, in a cell-dependent manner, crucial mechanisms of cancer migration and invasion, the key element of cancer metastasis." (PMID 37373092, 2023). "Interestingly, MT4-MMP silencing reduces HIF-1α- or SLUG-induced invasiveness and lung dissemination of cancer cells." (PMID 30654475, 2019). "Taken together, these results suggest that MT-4 does not interfere with the function of p-gp in cancer cells." (PMID 25874627, 2015). "It has been reported that MT4-MMP expression is induced by hypoxia through the hypoxia-inducible factor-1-α (HIF1-α) and the activation of SLUG, a known transcription factor involved in epithelial–mesenchymal transition (EMT) which promotes the malignant capacity of cancer cells." (PMID 37373092, 2023). "MT4-MMP was validated as a key signaling precursor and partner of EGFR, which enhances its activation leading to cancer cell proliferation in a non-proteolytic manner." (PMID 37373092, 2023). "We previously demonstrated that MT4-MMP is a key precursor and partner of Epidermal Growth Factor Receptor (EGFR), and enhances its activation leading to cancer cell proliferation in a non-proteolytic activity." (PMID 30654475, 2019).
tumor (9 papers, 2017 to 2025). "MT4-MMP is also expressed in tumor-associated macrophages (TAMs)." (PMID 37373092, 2023). "Similar to the mT4 cell findings, Neo1 knockdown in Panc02 cells improved mouse survival, decreased tumor-derived luciferase signals and histological tumor areas, and reduced Ki-67+ proliferating tumor cells in the splenic injection model." (PMID 40777309, 2025). "A direct contribution of MT4-MMP to tumor growth has been demonstrated by analyzing the proliferation index (Ki67 positivity) of MT4-MMP xenografts compared to control tumors." (PMID 37373092, 2023). "All this evidence opens the possibility for the use of MT4-MMP as an interesting potential therapeutic target against tumor progression." (PMID 37373092, 2023). "All this evidence opens the possibility of using MT4-MMP as an interesting potential therapeutic target against tumor progression." (PMID 37373092, 2023). "Although there are many ways by which MT4-MMP participates in tumor progression, the mechanisms used by this proteinase for epithelial–mesenchymal transition and vessel stability in tumors seem to recapitulate those described during embryonic development." (PMID 37373092, 2023). "In the same line, high levels of MT4-MMP expression in gastric tissues are associated with lymph node metastasis and serosal involvement, and therefore, with tumor invasion." (PMID 37373092, 2023). "Apart from MT1B, MT1F, and MT4, other MT isoforms in tumor tissue were both downregulated significantly in Oncomine and GEPIA databases." (PMID 31380415, 2019). "Previous studies have shown that MT4 promotes tumor growth and metastasis and influences cell proliferation." (PMID 28464030, 2017). "Whether the MT4-MMP–periostin axis plays a role in tumor cell development and progression deserves further investigation." (PMID 37373092, 2023). "Notably, MT4-MMP expressed by tumor cells was also found essential in promoting an early angiogenic switch and tumor blood vessel formation that has been shown to be dependent on its catalytic function." (PMID 37373092, 2023). "However, the molecular mechanisms by which MT4-MMP contributes to tumor development need further investigation." (PMID 37373092, 2023). "Interestingly, one key aspect of the role of Mt4-mmp in tumor physiology is that it contributes to vessel maturation and stabilization during tumor angiogenesis." (PMID 28926609, 2017). "Indeed, MT4-MMP requires a permissive microenvironment to exert its tumor-promoting effect." (PMID 37373092, 2023). "In lung metastasis, MT4-MMP alters blood vasculature and induces pericyte detachment, promoting tumor dissemination." (PMID 37373092, 2023). "Regarding MT4-MMP, although its function has been described mainly in relation to tumor cell growth, its expression is spatiotemporally controlled during embryonic development." (PMID 37373092, 2023). "According to the published reports, it seems that MT4- and MT6-MMP require a 3D extracellular tumor microenvironment for migration, invasion, and metastasis rather than 2D plasma conditions." (PMID 38310435, 2023). "MT4-MMP can be produced by immune cells promoting angiogenesis and retaining chemotactic molecules to attract them to the tumor neighborhood." (PMID 37373092, 2023). "All these data suggest that MT4-MMP presents unique functions and different substrates, promoting different pathologies, particularly in tumor progression." (PMID 30654475, 2019). "We also compared mT4-Lyt2-Luc-LA tumour burden in wild-type and STAT3f/f CreLysM mice and found delayed tumour growth in mice that lacked STAT3 expression in myeloid cells." (PMID 39886125, 2024). "Nevertheless, osteopontin proteolysis and JNK signaling that have been reported to be driven by MT4-MMP during vascular smooth muscle cell (VSCM) migration in the aorta vessel wall, might be relevant in the tumor vascular context." (PMID 37373092, 2023).
tumor (continued). "In this review, we aim to summarize the contribution of MT4-MMP in tumorigenesis, focusing on the molecular mechanisms triggered by the enzyme in tumor cell migration, invasiveness, and proliferation, in the tumor vasculature and microenvironment, as well as during metastasis." (PMID 37373092, 2023). "Tumor-derived MT4-MMP cannot circumvent the absence of a host angio-promoting factor such as the plasminogen activator inhibitor-1 (PAI-1), which cooperates with the uPA/uPAR axis in different contexts." (PMID 37373092, 2023). "For example, in contrast to most of MT-MMPs, MT4-MMP hydrolyses very few ECM components, and it also exhibits characteristic sensitivity to TIMPS as well as inefficient activation of pro-MMP2, which may explain its singular role in promoting tumor progression." (PMID 37373092, 2023).
infection (7 papers, 2018 to 2022). The state of being infected such as from the introduction of a foreign agent such as serum, vaccine, antigenic substance or organism. "We generated twelve IPMK-deficient MT4 target cell clones and six control clones and performed single cycle infection assays using HIV-1WT and HIV-1K359A/T371I." (PMID 34454514, 2021). "Among the differentially expressed gene (DEGS), metallothionein 4 (MT4) was found to be consistently downregulated during SE infection at all four postinfection time points." (PMID 34031125, 2021). "As patrolling monocytes have beneficial effects in infections and the prevention of lung metastasis, our results also suggest the therapeutic potential of boosting patrolling monocyte activity through MT4-MMP targeting." (PMID 29500407, 2018). "Therefore, we further speculate that consistent downregulation of the MT4 gene during SE infection in chicks may have a consequential effect on host defense response, with a potential failure to induce effective IL-2 expression." (PMID 34031125, 2021). "Finally, patrolling monocytes have beneficial intravascular actions in infection, lung metastasis, and Alzheimer’s disease, and our results suggest that short-term MT4-MMP targeting may offer a new therapeutic strategy to boost these activities." (PMID 29500407, 2018).
MT4 also shares sentences with these, for which no sentence is quoted: cardiovascular disease (2 papers); bacterial infection (1); COVID-19 (1); craniopharyngioma (1); entropion (1); head and neck squamous cell carcinoma (1); Hydrocephalus (1); Hypernatremia (1); lung carcinoma (1); lymph node metastasis (1); meningioma (1); metastatic disease (1); periodontitis (1); pinealoma (1); poisoning (1); ulcerative colitis (1).